PGR (progesterone receptor)
Diseases named in the same sentence as PGR in open-access papers (continued):
Sharing a sentence is not in itself a finding about the gene and the disease.
breast cancer (continued). "In order to better understand the biological characteristics of BBD, a few authors have focused on estrogen receptor (ER) 7, 8, progesterone receptor (PR) 9, and Ki67 7, 10, 11 as biomarkers expressed in benign lesions that are not in proximity to concomitant breast cancer." (PMID 28470951, 2017). "We used the well-established TumorGraft TM mouse models of triple negative (TNBC) and progesterone receptor positive (PR+BC) breast cancer, and profiled global microRNAome changes in tumor-bearing mice upon chemotherapy, as compared to untreated tumor-bearing mice and intact mice." (PMID 29179434, 2017). "The presence or not of ER and PgR helps determine a possible relapse of breast cancer." (PMID 28173783, 2017). "Drug-refractory breast cancers include HER2+ tumors that have acquired resistance to HER2-targeted antibodies and kinase inhibitors, and “Triple-Negative” Breast Cancers (TNBCs) that lack the therapeutic targets Estrogen Receptor, Progesterone Receptor, and HER2." (PMID 28423644, 2017). "Replication in larger studies using estrogen receptor (ER)-negative or triple-negative (i.e., ER-, progesterone receptor-, and HER2-negative) cases could therefore be helpful to confirm the association of this locus with breast cancer risk." (PMID 27796716, 2017). "This study addressed the question whether the recently developed molecular in vitro diagnostic MammaTyper® test could improve the reproducibility of the assessment of the four key routine breast cancer biomarkers ERBB2 (HER2), ESR1 (ER), PGR (PgR), and MKI67 (Ki67)." (PMID 28490348, 2017). "Assessing the degree or patterns of spatial intratumoral TILs heterogeneity might also be an option for a more detailed description of the immune response status of the tumor, as recently suggested for ER/PgR negative breast cancer." (PMID 26506242, 2016). "HDL in diabetic breast cancer patients in contrast to nondiabetic patients may promote migration and invasion in both ER/PgR positive and PgR/ER receptor negative breast cancer through ERK and p38 MAPK pathways." (PMID 26970778, 2016). "On the contrary, the levels of AKT3 mRNA, protein, and enzymatic activity are significantly increased in estrogen receptor negative (ER−) and triple negative (ER−, Progesterone Receptor negative, Her2/neu negative; ER−PR−Her2/neu−) breast cancers, promoting cell proliferation and tumor growth." (PMID 27323778, 2016). "Specifically, AI/AN women had 2.3 fold higher odds of presenting with stage IV breast cancer compared with non-Hispanic White women, and 1.3 fold higher odds of being diagnosed with estrogen receptor (ER)-/progesterone receptor (PR)- breast cancer compared with non-Hispanic White women." (PMID 29546205, 2016). "Triple negative breast cancer (TNBC) is a specific breast cancer subtype that is immunohistochemically negative for expressions of prognostic markers including estrogen receptor (ER), progesterone receptor (PR), and human epidermal growth factor receptor 2 (HER2)." (PMID 27589736, 2016). "Triple-negative breast cancer (TNBC) is a hypotype of breast cancer that is immunohistochemically based on the negative expression of the hormone receptors estrogen receptor (ER) and progesterone receptor (PR) and on the negative amplification of HER2 amplification." (PMID 27561099, 2016). "The most common classification system for breast cancer is presently based on histological type, tumor grade, lymph node status and the presence of predictive markers such as estrogen receptor alpha (ESR1), progesterone receptor (PGR) and epidermal growth factor receptor (HER2)." (PMID 26783963, 2016). "Thus, immunohistochemical Ki67 assay, together with ER, PgR and HER2 status, was chosen as a useful and easily-to-apply surrogate for gene expression profile to defined breast cancer molecular subtypes, despite a lesser analytical validity than molecular testing and a reliable clinical validation." (PMID 27000271, 2016).
breast cancer (continued). "Moreover, obese young breast cancer patients were found to have larger tumors, higher grade, and were more often ER negative and PgR negative, and the oxysterol, 27OH-Cholesterol, is associated with hormone receptor positive breast cancer cell proliferation." (PMID 26970778, 2016). "While the GAS5 HREM interacts with progesterone receptor, this interaction is unlikely to play a major role in breast cancer cell survival, since both GAS5 lncRNA and the GAS5 HREM sequence induce apoptosis in TNBC cells which are devoid of progesterone receptors." (PMID 26862727, 2016). "However, there is no promising treatment that is effective for triple negative (TN) breast cancer, defined as ER negative, PgR negative, and HER2 negative." (PMID 26217553, 2015). "Several factors may alter the HR status of a breast cancer, resulting in a false-negative ER and/or false-positive PgR assay." (PMID 26161666, 2015). "Currently, biomarkers such as ER, Progesterone Receptor (PgR) and the Human Epidermal growth factor-like Receptor 2 (HER2) expression level, as well as proliferation status as measured by Ki-67, roughly distinguish patients according to breast cancer subtypes and help inform treatment choice." (PMID 26473850, 2015). "Similarly, although progesterone and the progesterone receptor play important roles in mammary gland development and breast cancer progression, no progesterone assays have been adopted into EDSP or other mainstream chemical testing paradigms." (PMID 26032647, 2015). "In breast cancer, KLK9 expression was also higher in patients with smaller tumors and was associated with increased patient survival, particularly patients that are estrogen and progesterone receptor negative." (PMID 26231762, 2015). "Regarding predictive factors for breast cancer, high EZH2 expression was significantly associated with the absence of estrogen receptor (positive vs. negative: OR 0.15, 95% CI: 0.11–0.20) and progesterone receptor (positive vs. negative: OR 0.30, 95% CI: 0.23–0.39) expression." (PMID 25974088, 2015). "Triple negative breast cancer (TNBC), defined by the lack of expression of the estrogen receptor, progesterone receptor and human epidermal receptor 2, is an aggressive form of breast cancer that is more prevalent in certain populations, in particular in low- and middle-income regions." (PMID 25961742, 2015). "Indeed, VDR knock-out mice are more likely to develop ER- and progesterone receptor (PR)- negative mammary tumors as compared with their wild type littermates, highlighting calcitriol prodifferentiating properties." (PMID 24678876, 2014). "In this study we investigated matrix hyaluronan (HA)-CD44 (a primary HA receptor) interaction with c-Jun N-Terminal Kinase (JNK)/c-Jun signaling in MDA-MB-468 breast cancer cells [a triple-negative (estrogen receptor-negative/progesterone receptor-negative/HER2-negative) breast cancer cell line]." (PMID 24606718, 2014). "The basal-like molecular subclass of human breast cancers is characterized by increased expression of HIF target genes and largely overlaps with the triple-negative clinical subclass of breast cancers that lack expression of the estrogen receptor, progesterone receptor, and HER2." (PMID 25587023, 2014). "In addition certain sporadic breast cancers may have hypermethylation of the BRCA1, estrogen receptor (ER), progesterone receptor (PR) and other genes which prevents or lowers their expression." (PMID 25051360, 2014). "The first study to use this approach involved applying SNS to study the evolution of aneuploidy in patients with triple-negative (ER-/PR-/HER2-) breast cancers (TNBCs; negative for, respectively, the estrogen receptor, progesterone receptor and the receptor tyrosine-protein kinase erbB-2 (HER2))." (PMID 25222669, 2014).
breast cancer (continued). "Altogether, our data indicate that in ERα-positive postmenopausal breast cancer patients, PIK3CA mutations are not enriched in lobular breast cancer, but are associated with favorable prognostic factors like low grade and positive PgR status." (PMID 24467828, 2014). "Our analysis of a breast cancer dataset finds that the positive feedback loops across 7 genes, AR, ESR1, MYC, E2F2, PGR, BCL2 and CCND1 are conserved across the basal/triple negative subtypes in multiple datasets that could potentially explain the aggressive nature of this cancer subtype." (PMID 23368093, 2013). "Thus, in an unbiased genome-wide search for the most prognostic markers in ER+ breast cancer, progesterone receptor would be unlikely to be selected." (PMID 23971947, 2013). "This has included studies in various breast cancer subtypes wherein breast cancers are characterized by the presence of receptors such as estrogen receptor (ER), progesterone receptor (PR), and HER2/ErbB2 receptor (HER2) or by the absence of all of them, the triple negative breast cancers (TNBCs)." (PMID 23533807, 2013). "Triple-negative breast cancer (TNBC), a subtype of breast cancer with negative expressions of estrogen receptor, progesterone receptor, and human epidermal growth factor receptor 2 (HER2), is frequently diagnosed in younger women and has poor prognosis for disease-free and overall survival." (PMID 24216290, 2013). "The patient who developed grade 3 encephalopathy was symptomatic at baseline from multiple brain metastases, was the oldest patient enrolled (76 years old), and was heavily pretreated for her disease (breast cancer, estrogen receptor/progesterone receptor positive, HER2/neu negative)." (PMID 23965287, 2013). "Triple-negative breast cancer (TNBC) is an aggressive clinical subtype of breast cancer that is characterized by the lack of estrogen receptor (ER) and progesterone receptor (PR) expression as well as human epidermal growth factor receptor 2 (HER2) overexpression." (PMID 24188694, 2013). "In May 2002, left-sided breast cancer was detected (grade 2, pT2, N1bIII, N0, oestrogen receptor negative, progesterone receptor negative)." (PMID 24596658, 2013). "Therefore, identification of novel therapeutic targets is essential to combat breast cancers, especially those lacking estrogen receptor/progesterone receptor and ErbB2 receptor (triple negative breast cancer)." (PMID 25068070, 2013). "Furthermore, the expression of the EGFR is twice as likely in breast cancers which are “double negative”, lacking both the ER and the progesterone receptor (PR)." (PMID 23434903, 2013). "Estrogen receptor (ER), progesterone receptor (PR), and human epithelial growth factor receptor 2 (HER2) are recognized as common clinical tumor markers for tumor growth and progression and as indicators of determining appropriate therapy for patients with breast cancer." (PMID 23710200, 2013). "Triple negative breast cancer (TNBC) in humans is a distinct subset of breast cancer that is defined by the lack of immunohistochemical (IHC) expression of the oestrogen receptor (ER) and progesterone receptor (PR) and a lack of human epidermal growth factor receptor 2 (HER2) overexpression." (PMID 23587222, 2013). "However, triple negative breast cancer (TNBC) is a type of breast cancers that does not express the genes for estrogen receptor (ER), progesterone receptor (PR) or human epidermal growth factor receptor 2 (HER2)." (PMID 22905152, 2012). "This work suggests that unfavorable genetic variants in the rs207454 (XDH) and rs3736729 (GCLC) polymorphisms may act as predictors of the outcome in negative progesterone receptor and negative estrogen receptor breast cancer patients, respectively." (PMID 23443115, 2012).
breast cancer (continued). "The roles of female sex hormones such as progesterone (P4) in the pathogenesis of breast cancer remain unclear and the function of P4 in progesterone receptor negative (PR–) or basal phenotype breast cancer (BPBC) is even less well understood." (PMID 22496908, 2012). "In breast cancer, HSP90 is required for the stabilization of many proteins in pathways that play key roles in cancer growth and survival, such as estrogen receptor (ER), progesterone receptor (PR), essential components of HER2 signaling (HER2, AKT, c-SRC, RAF and HIF-1α), and EGFR." (PMID 22510516, 2012). "Therefore inhibition of the progesterone receptor has not been established in the treatment of human breast cancer so far." (PMID 23236990, 2012). "The immunohistochemical reaction for the markers, which are routinely investigated in colorectal (CEA, CK20) and breast cancers (ER, PgR, Ki67 and HER2) gave results indistinguishable from those obtained from the samples of the same cases processed by standard method." (PMID 21698245, 2011). "After biopsy revealed an estrogen receptor positive and progesterone receptor negative breast cancer, followed by surgical resection of the invaded sentinel lymph nodes, a neoadjuvant chemotherapy (four cycles Epirubicin/Cyclophosphamide, followed by four cycles of Taxotere®) was applied." (PMID 24212668, 2011). "The basal subtype of human breast cancer is typically triple-negative (estrogen receptor, progesterone receptor, and HER2/neu negative), and as a consequence has a poor prognosis, as it is most often poorly responsive to many of the current treatment strategies." (PMID 21541295, 2011). "The finding of ER/PgR-positive DCIS in some patients with ER/PgR-negative breast cancer may be clinically relevant and may necessitate a more careful analysis of the tissue for this setting." (PMID 22091428, 2011). "However, about 10% to 15% of breast cancers do not express ER, progesterone receptor (PR), and HER2/Neu receptor." (PMID 21435243, 2011). "Triple negative (TN) breast cancers are defined as the absence of estrogen receptor (ER), progesterone receptor (PR) and HER2 expression, accounting for 10-17% of all breast carcinomas depending on the threshold used to define ER and PR positivity and the methods for HER2 assessment." (PMID 21396129, 2011). "Consistent with this notion, we recently found significantly higher frequency of CT mRNA expression in estrogen receptor (ER) and progesterone receptor (PR) negative breast cancer cell lines and primary breast cancers, including MAGE-A3, MAGE-A6, NY-ESO-1, MAGE-A12, LAGE-1, CSAG2 etc." (PMID 21437249, 2011). "The remaining 10–15% of breast cancers is negative for ER, PgR and HER2." (PMID 22933934, 2011). "Both were in women with breast cancer – one had a triple negative breast cancer (ER and progesterone receptor (PR) negative, HER2 negative) that was PIK3CA wild type, without PTEN loss and KRAS mutant; and the other had a ER/PR positive, HER2 negative tumor with a confirmed PIK3CA mutation (E545K)." (PMID 21317449, 2010). "In sporadic breast cancer, absent or reduced BRCA1 expression was associated with high tumor grade, advanced lymph node stage, larger size, vascular invasion, negative estrogen receptor, negative progesterone receptor and poor outcome." (PMID 20209131, 2010). "For many years, breast cancers were classified by whether or not they express various receptors, namely the estrogen receptor (ER/EsR1), the progesterone receptor (PR/PGR) and ErbB2." (PMID 19317917, 2009). "Interestingly, this lifetime protective effect is limited to oestrogen receptor-positive/progesterone receptor-positive (ER+PR+) breast cancers and is not seen for other breast tumour types." (PMID 19386118, 2009).
breast cancer (continued). "In particular, the results of the present study indicate that RFS at 2 years after primary therapy and surgery is significantly worse in the cohort of patients with ER- and PgR-negative tumours compared with ER-positive breast cancer, either in the NIBC or in IBC group." (PMID 18506176, 2008). "Interestingly, DKK1 was preferentially expressed in oestrogen and progesterone receptor-negative tumours (ER−/PR−; P=0.005) and in tumours from women with a family history of breast cancer (P=0.024)." (PMID 17245340, 2007). "Sixty-four percent of breast carcinomas with negative oestrogen receptors (ER) and 55% of those with negative progesterone receptor (PR) status express significantly higher levels of VEGF-A than hormonal receptor positive carcinomas (P<0.001 and P=0.004, respectively)." (PMID 17353919, 2007). "She had a previous history of modified mastectomy with axillary lymphadenectomy for a retroareolar, canalicular breast carcinoma 6 months before, whose histological diagnosis was a ductal carcinoma measuring 4.5 cm of diameter, estrogen and progesterone receptor-positive and HER2 negative." (PMID 17244373, 2007). "Triple-negative breast cancer (TNBC) is one of the most aggressive subtypes of breast cancer (BC), lacking the expression of estrogen receptor (ER), progesterone receptor, and human epidermal growth factor receptor 2 (HER2)." (PMID 41007774, 2025). "Molecular and histological profiling classifies BC into three major subtypes: those expressing the hormone receptors of BC (estrogen receptor (ER) or progesterone receptor (PR)), those expressing human epidermal growth factor receptor 2 (HER2) of BC, and triple-negative breast cancer (TNBC)." (PMID 41268576, 2025). "Worldwide, breast cancer has become the most diagnosed cancer with ~15% of these cases being triple negative, which is defined by absent/low expression of the hormone receptors, estrogen receptor and progesterone receptor, and lack of amplification of human epidermal growth factor receptor 2 (HER2)." (PMID 40089851, 2025). "Triple-negative breast cancer (TNBC) accounts for 10–20% of invasive BC cases and is defined by the absence of estrogen receptor (ER), progesterone receptor (PR), and human epidermal growth factor receptor 2 (HER2)." (PMID 38786030, 2024). "TNBC is a particularly aggressive subtype of breast cancer (BC) characterized by the absence of estrogen receptor, progesterone receptor, and HER2 amplification." (PMID 39512697, 2024). "Triple–negative breast cancer (TNBC) is an aggressive subtype accounting for ~10–20% of all human BC and is characterized by the absence of estrogen receptor (ER), progesterone receptor (PR), and human epidermal growth factor receptor 2 (HER2) amplification." (PMID 37835573, 2023). "Approximately 15–20% of breast cancer cases belong to the triple-negative breast cancers subtype (TNBCs), which is known to be the most aggressive subtype characterized by the absence of estrogen receptor, progesterone receptor, and human epidermal growth factor receptor 2 amplification." (PMID 37569595, 2023). "Triple-negative breast cancer (TNBC) is a heterogeneous and invasive breast cancer (BC) subtype that is estrogen receptor-negative, progesterone receptor-negative, and human epidermal growth factor receptor 2 (Her2)-negative." (PMID 36438660, 2022). "According to histological expression of three receptor proteins, estrogen receptor (ERα; ESR1), progesterone receptor (PGR), and human epidermal growth factor receptor 2 (ERBB2; HER2; Neu), BC is divided into Luminal A, Luminal B, HER-2 positive, and triple-negative breast cancer (TNBC)." (PMID 36345017, 2022). "Clinical classification of BC based on the expression of the estrogen receptor (ER), progesterone receptor (PR) and human epidermal growth factor receptor 2 (HER2) has resulted in three broad subtypes, which are luminal BC, HER2-positive (HER2+) BC and triple-negative breast cancer (TNBC)." (PMID 36077333, 2022).